TNF (tumor necrosis factor)
Diseases named in the same sentence as TNF in open-access papers (continued):
Sharing a sentence is not in itself a finding about the gene and the disease.
cancer (continued). "For example, PD-L1 expression and the PD-1 checkpoint pathway are involved in cancer, while the T-cell receptor signaling pathway, Th17 cell differentiation, the TNF signaling pathway, the IL-17 signaling pathway, and Th1 Th2 are involved in cell differentiation." (PMID 38482051, 2024). "Notably, most of the genes were enriched in pathways in cancer, TNF-alpha signaling pathway, apoptosis, IL17 signaling pathway, Th17 cell differentiation, toll-like signaling pathway, HIF1 signaling pathway, and osteoclast differentiation." (PMID 39640488, 2024). "Notably, adipocytes co-cultured with cancer cells displayed a marked increase in TNFα signaling, which can regulate the expression of various adipokines." (PMID 38744820, 2024). "We thus investigated whether IL‐17A influences the TNF‐driven adhesion of cancer cells to a mesothelial monolayer in vitro." (PMID 38566518, 2024). "By lowering TNF-α, curcumin may help mitigate chronic inflammation, potentially slowing or preventing cancer progression driven by inflammation." (PMID 39816400, 2024). "In addition, the coculturing of adipocytes with cancer cells also increased TNF-α expression in adipocytes." (PMID 39040042, 2024). "According to the literature, a significant increase in the levels of pro-inflammatory mediators, primarily pro-inflammatory cytokines like interleukin (IL)-6 and tumor necrosis factor (TNF), is closely associated with increased proliferation and enhanced survival of cancer cells." (PMID 38337668, 2024). "Conversely, TNF-α is a proinflammatory cytokine produced by immune system cells and cancer cells." (PMID 39409068, 2024). "A meta-analysis revealed that the use of TNF inhibitors in IMID patients with a history of cancer was not linked to a higher risk of cancer recurrence or the development of new cancers." (PMID 39272800, 2024). "Its immune-modulating effects, such as enhanced NK cell activity and reduced levels of pro-inflammatory cytokines like IL-6 and TNF-α, may further contribute to its anti-cancer properties." (PMID 39597826, 2024). "Additionally, there appears to be a correlation between vitamin D and other inflammatory factors such as TNF-alpha, IL-1 beta, IL-6, IL-8, and IL-10, as well as its involvement in autoimmune diseases and cancers." (PMID 38337827, 2024). "Furthermore, our study also discovered that under the induction of SPP1, pro-cancer genes such as Arg1 and Nos2 were upregulated in MDSCs, while anti-cancer genes like IL1b and TNFα were downregulated." (PMID 39066845, 2024). "Moreover, PML nuclear bodies regulate TNFα-induced cell death in cancer cells and suppress capillary tube formation and migration in endothelial cells." (PMID 38118002, 2024). "TNF-α is necessary for the development and spread of cancer." (PMID 38654309, 2024). "In HCC cells, TNF-α has been characterized as a pro-tumor factor because its increased expression is associated with the activation of the NF-κB and JNK pathways, promoting carcinogenesis and supporting cancer cell survival and migration." (PMID 39409068, 2024). "Likewise, the activation of tumor necrosis factor alpha (TNF-α) and multiple inflammatory cytokines, including IL-6, IL-10, and IL-23, play a critical role in the cancer-promoting mechanisms associated with certain microbes." (PMID 39596994, 2024). "Besides, previous literatures have reported H2AFY facilitated the response of cancer cells to TNFα-NF-κB pathway." (PMID 38245506, 2024). "Regarding cancer, the role of TNF-α is a double-edged sword." (PMID 39411143, 2024).
cancer (continued). "Besides, circulating inflammatory cytokines, e.g., TNF-α, IL-6, and IL-10 are discussed as potential prognostic oncomarkers in BC patients due to their contribution to cancer proliferation and invasion." (PMID 38464730, 2024). "Additionally, cancer increases the levels of various pro-inflammatory cytokines, including IL-1, IL-6, and TNF-α, which contribute to the development of cachexia and oxidative damage." (PMID 38791998, 2024). "Furthermore, increasing evidence indicates that the enhanced catabolism experienced by cachectic cancer patients is mediated primarily by increases in pro-inflammatory cytokines, including TNF-α, IL-1, and IL-6." (PMID 38339292, 2024). "The ethanolic extracts of Argemone mexicana Linn have been found to exhibit anti-inflammatory properties by downregulating TNF-α expression and modulating NF-kB-p65 transcription factor activity, suggesting their potential therapeutic efficacy in inflammatory and cancer-related conditions." (PMID 39687882, 2024). "The active compound 6-chloro-N-(4-nitrobenzyl) benzo[d] thiazol-2-amine (compound B7) was screened through a series of bioactivity assessments, which significantly inhibited the proliferation of A431, A549 and H1299 cancer cells, decreased the activity of IL-6 and TNF-α, and hindered cell migration." (PMID 38562527, 2024). "Cancer cell secretion of TNFα can promote DC production, differentiation, and maturation." (PMID 38461238, 2024). "Our results support the ambivalent effects of TNF-α on cancer apoptosis." (PMID 38464730, 2024). "In contrast, depletion of DiPRO1 in cancer cells induced activation of signaling pathways for inflammation (TNF/TNFR1/2, inflammasome, neuroinflammation), stress response (MAPK signaling), and apoptosis (intrinsic pathway, apoptotic execution, and HIV1 induction of apoptosis)." (PMID 39009887, 2024). "TNF‐α has been shown to promote chemoresistance through several mechanisms, including activation of the NF‐κB pathway, regulation of drug efflux, induction of the cancer stem cell phenotype, and modulation of the TME." (PMID 38750006, 2024). "Notably, both SMCs and TEXs significantly enrich in TNF-α signaling via NF-κB and EMT signaling pathways, both intimately associated with malignant tumor metastasis, particularly EMT." (PMID 38683136, 2024). "Constitutive secretion of TNF-α is observed in many cancer types." (PMID 39201656, 2024). "For downregulated lncRNAs, their interacting genes were enriched in immune regulation processes, such as hematopoietic or lymphoid organ development and negative regulation of T cell activation and in cancer-related functions, such as response to tumor necrosis factor." (PMID 38229597, 2024). "Moreover, the highly enriched signaling pathways primarily included the PD-L1 expression and PD-1 checkpoint pathway in cancer, Th17 cell differentiation, the TNF signaling pathway, and the HIF-1 signaling pathway." (PMID 39339615, 2024). "Then, jacaranone effectively inhibits TNFα-induced NF-κB activation by suppressing IκBα degradation, impeding NF-κB transcriptional activity, and preventing p65 nucleation in different cancer cell lines." (PMID 39769432, 2024). "The limited therapeutic efficacy of TNF-α inhibition in cancer settings might support, at least in part, this finding." (PMID 38989743, 2024). "In the clinical setting, anti-TNFα inhibitors are now entering clinical trials to treat cancers." (PMID 36980717, 2023). "However, in the elderly, TNF-α can participate in a variety of pathological processes, such as inflammaging, autoimmunity, and cancer." (PMID 38087369, 2023). "TNF-alpha also mediates cancer-related inflammation through the activation of NF-kB." (PMID 38332913, 2023). "siRNA transfection induced knockdown of IFN-γ and TNF-α in doxorubicin-treated B16F10 cancer cells." (PMID 36854774, 2023).
cancer (continued). "The expression of TNF-α and regulation of the NF-κB signalling pathway were also studied and found to be reduced significantly (p < 0.001), which helped with the prevention of cancer." (PMID 38067358, 2023). "Furthermore, H. pylori infection is also known to stimulate the production of proinflammatory cytokines such as IL-1β, TNF-α, and IL-6, thus creating a microenvironment that promotes cancer cell growth and survival." (PMID 37325512, 2023). "In addition, PRRE not only inhibited cancer cell invasion, but also promoted tumor necrosis factor-alpha (TNF-α)-induced cell death." (PMID 36830802, 2023). "Moreover, TNF-α has been reported to drive tumor eradication and progression in cancer patients, depending on the dose and cancer type." (PMID 36829966, 2023). "Carnitine can also decrease the elevated serum levels of IL-6 and TNF-α in cancer cachectic mice." (PMID 37600065, 2023). "However, ligands like FasL, TNF-α, and Apo are mainly produced by activated macrophages and interact with specific death receptors, thereby initiating the apoptosis process in the cancer cells." (PMID 37560308, 2023). "Thus, the repeated identification of TNFα suggests that it is a critical and conserved pan-cancer pathway involved in metastasis." (PMID 36980717, 2023). "However, this nomenclature ignores that some of the inflammatory “M1” characteristics, like iNOS or TNF-α production can also fuel cancer progression." (PMID 36845555, 2023). "Since RIME is induced by TNF‐α and upregulated in cancer cells, targeting RIME might reduce the adverse effect of epigenetic modifier inhibitors on normal cells and has tremendous potential to improve antitumour immune responses." (PMID 37712124, 2023). "Multiple meta-analyses reported no increased overall risk of cancer in IBD patients with anti-TNF therapy." (PMID 36983432, 2023). "TNF-α appears to have contradictory effects on almost every type of cancer." (PMID 37534280, 2023). "TRAIL belongs to a group of the tumor necrosis factor (TNF) family that is involved in the apoptosis of cancer cells via the death receptors DR4 and DR5 without causing cytotoxicity in normal cells, making it a potential antitumor agent." (PMID 37514119, 2023). "Conversely, genes with high votes but low cancer prevalence may be involved in the NFκB/TNF pathway in a cancer-specific manner." (PMID 37475016, 2023). "Commonly known as a participant in maintaining homeostasis of cancer immunobiology, TNF-α unveils its ‘dark side’ to provoke chronic inflammation, EMT and angiogenesis, which may fuel the aggressiveness of cancers." (PMID 37261338, 2023). "The upregulation of plasma levels of VEGF-A, TNF-α, CCL2, IL-6, and IFN-γ in Cancer TIF1-γ-DM patients could provide insight into the underlying mechanism of the pathogenesis of Cancer TIF1-γ-DM." (PMID 36357631, 2023). "The flavonoid dihydroquercetin, extracted from onions, promotes anti-cancer and anti-inflammatory effects via the induction of apoptosis in cancer cells and the inhibition of pro-inflammatory agents, including NF-kB, TNFα, IL-1β, and IL-6, in LPS-treated cancer and immune cells." (PMID 38140352, 2023). "Therefore, the following review aims to summarize an up-to-date overview of the current experimental and clinical evidence of the anesthesia implications on cancers based on the insights of TNF-α release." (PMID 36765695, 2023). "Of note, a significant fraction of the genes targeted by these gRNAs were connected to 7 cellular processes that are potentially druggable for cancer treatment such as apoptosis, autophagy, cell cycle, as well as the NF-κB, tumor necrosis factor (TNF) and toll-like receptor (TLR) signaling pathways." (PMID 37623817, 2023).
cancer (continued). "Bone loss is mainly caused by the activation of osteoclastogenesis via the RANK/RANKL (receptor activator of nuclear factor kappa-B ligand) signaling in response to proinflammatory and proosteolytic cytokines such as interleukin-1, 6, and tumor necrosis factor-α secreted by cancer cells." (PMID 38067217, 2023). "AS patients treated with anti-TNF therapy did not demonstrate an excessive or reduced risk of solid or hematologic malignancies." (PMID 37568555, 2023). "In addition, previous preclinical and clinical findings from aggressive human upper aerodigestive tract cancer showed that cancer-related pre-inflammatory genes, such as TNF-α, and IL-1β, were significantly overexpressed during this process." (PMID 37259369, 2023). "Consequently, although maintaining normothermia during cancer surgery is recommended, the effect of body temperature control on the release of TNF-α and cancer outcomes warrants further investigations." (PMID 36765695, 2023). "Furthermore, KEGG pathway analysis revealed that TRIM28 regulates several cancer-associated pathways such as the PI3K-AKT, TNF, and PPAR pathways." (PMID 37357254, 2023). "Medicines that down-regulates TNF-α and IL-1 have been shown to improve cancer cachexia." (PMID 37641070, 2023). "The proinflammatory cytokine TNF‐α exerts an essential role within the host's immune response, whereas many studies have recently reported its dual role in the initiation and progression of cancers." (PMID 35871313, 2023). "TNF-α is well known for its modulation of many important signal transduction pathways such as inflammation and cell proliferation, which are very important in controlling cancer cell survival." (PMID 37760972, 2023). "These demonstrate esethat TNF-α plays a key role in cancer cachexia." (PMID 37533569, 2023). "Therefore, it cannot be concluded that anti-TNFα mAb is effective against other organ cancers and CRC based only on the results of this study." (PMID 36996146, 2023). "When TNF-α was first discovered in 1975, it was regarded as an antitumor cytokine that was able to facilitate the vascular destruction of cancer cells and exert a synergistic effect with chemotherapy at cancer sites." (PMID 37212877, 2023). "It was speculated that TNF-α could induce the expression of the KLF5-EphA2 axis to promote cancer stemness." (PMID 37063424, 2023). "TNFα has been highlighted as a crucial mediator of cancer-related inflammation and thus its targeting may be a key to oncological therapy resistance." (PMID 36980727, 2023). "Similarly, the overexpression of TNF-alpha was found in numerous cancers including ovarian, breast, and colorectal." (PMID 37753372, 2023). "We assessed the predictive significance of NF-κB p65 (RelA) and TNFα in cancer using GEPIA to determine whether the expression levels of these proteins are connected to the prognosis of cancer patients." (PMID 37892820, 2023). "Similarly, depriving cancer cells of glutamine can enhance their sensitivity to apoptosis induced by TNF-α and heat shock." (PMID 37765194, 2023). "Therefore, natural phytochemicals are potent oncogenic inhibitors by regulating inflammation through regulating TNF‐α mediated NF‐κB, IκB kinase, COX‐2 and MMP‐8, IL‐1β, TNF‐α, phospho‐Akt, phosphor‐p65, and NF‐κB‐binding activity in numerous cancer models." (PMID 37132286, 2023). "Studies have shown that radiofrequency electrodes can coagulate and necrosis cancer cells through high temperature and can stimulate the body to produce cytokines such as tumor necrosis factor-α (TNF-α), interleukin-1 (IL-1), and interleukin-6 (IL-6) to inhibit the growth of cancer cells." (PMID 37817253, 2023). "For instance, in cancer, TNF can have both anti-tumor and pro-tumorigenic effects." (PMID 36968066, 2023). "However, a series of preliminary studies have demonstrated that, depending on the cancer type, TNF-α can promote or inhibit apoptosis in tumor cells." (PMID 37736898, 2023).
cancer (continued). "Macrophages as well as dendritic cells can also be important producers of IL-1β and TNF-α, suggesting that cytokine therapy in addition to Salmonella therapy could be of potential value in cancer therapy." (PMID 37588093, 2023). "In addition to its role in cell death, RIPK1 abrogates tumor necrosis factor (TNF) signaling via nuclear factor kappa-B (NF-κB) in cancer cells." (PMID 37516007, 2023). "In addition, cancer-stimulated production of inflammatory cytokines (e.g., tumor necrosis factor-α, IL-1, IL-6, and interferon-γ) inhibits erythropoiesis and leads to Hb decline." (PMID 36661734, 2023). "Moreover, they were enriched in the TNF signaling, transcriptional misregulation in cancer, and NF-kB signaling pathways." (PMID 36969001, 2023). "TNFα is secreted by stromal cells, mainly by TAMs, and cancer cells." (PMID 37208442, 2023). "High plasma TNF levels have been observed in some cancer patients with poor prognoses." (PMID 36357631, 2023). "TNF-α, similarly to IL-6, is a proinflammatory cytokine characterized by a broad spectrum of functions which also include cytotoxic and cytostatic effects against cancer cells and in MCF-7 cells." (PMID 36903346, 2023). "TNF-α also induces cancer cell apoptosis through the MAPK-JNK pathway." (PMID 38001420, 2023). "Indeed, cytokines such as IL-6, TNF-α, and TGF-β have been closely related to cancer-associated muscle wasting, since they disrupt muscle proteostasis, as well as mitochondrial biogenesis and function." (PMID 38136400, 2023). "Additionally, TNFα is a pro-inflammatory cytokine that was reported as overexpressed in BC, where it correlates with augmented cancer cell proliferation, increased metastasis, higher malignancy grade, and poor prognosis." (PMID 37834160, 2023). "The definitive role of TNFα in the immune response to cancer is still debated." (PMID 37461742, 2023). "Anti-TNF medications are typically not used for people who have a high risk of cancer since they seem to be more immunosuppressive." (PMID 38139369, 2023). "The typical proapoptotic function of pro-inflammatory cytokines (IL-1β, TNF-α, and IL-6) can actually increase cancer cell survival via mitogen-activated protein kinase/extracellular signal-regulated kinases (MAPK/ERK) or phosphoinositide 3-kinase/ protein kinase B (PI3K/Akt)-dependent pathways." (PMID 37555952, 2023). "Inflammatory markers and fatigue are closely related during the treatment of cancer patients, with high levels of interleukin 6 (IL-6), interleukin 1 (IL-1), and tumor necrosis factor-alpha positively correlating with the degree of fatigue after chemotherapy in cancer patients." (PMID 37542585, 2023). "Daily consumption of dark tea can achieve cancer prevention by inhibiting pro-inflammatory cytokines TNF-α, IL-1β, and IL-6 and increasing anti-inflammatory cytokines IL-10 and IL-22, which is mainly attributed to the down-regulation of the NF-κB signaling pathway." (PMID 37764687, 2023). "Interestingly, TNFα boosts the production of estradiol, which binds to ER and encourages the growth of luminal cancer cells." (PMID 37869088, 2023). "However, with the in-depth exploration of TNF-α, it has been revealed that TNF-α also contributes to inflammation and cancer growth." (PMID 37212877, 2023). "In the context of cancer, TNF binds its receptors TNF-RI and TNF-RII to promote cell proliferation." (PMID 37809067, 2023). "Herein, a significant increase in IL-1β, IL-6, and TNF-α serum levels was detected that could support the role of proinflammatory cytokines in cancer patients." (PMID 37068081, 2023). "These proinflammatory cytokines are generally responsible for immune response activation (i.e., IL-6), cytotoxic and cytostatic effects against cancer cells (i.e., TNF-α), and the recruitment and activation of immune cells along with other pro-inflammatory cytokines (i.e., IL-1β)." (PMID 37760610, 2023).